IGF1 (insulin like growth factor 1)
Diseases named in the same sentence as IGF1 in open-access papers (continued):
Sharing a sentence is not in itself a finding about the gene and the disease.
steatosis (33 papers, 2015 to 2025). Increased lipid within the cytoplasm of cells. "Apart from steatosis, different studies have associated the levels of IGF-1 and GH with the development of fibrosis." (PMID 36831184, 2023). "Steatosis in humans has been associated with low circulating GH levels and IGF1 levels, as well as inactivating mutations in the GHR." (PMID 34685512, 2021). "In a model of Western diet-induced NAFLD in mice, steatosis was associated with a 40% decrease in IGF-1 hepatic expression." (PMID 30200408, 2018). "Associations between IGF1 serum levels and steatosis, in NAFLD/NASH patients, are also presented in literature, but there are some differences in the presented data." (PMID 29702590, 2018). "Indeed, low levels of GH and IGF-1 were generally associated with a higher degree of fibrosis, steatosis, hepatic inflammation, and hepatocellular injury, the four main components responsible for the progressive development of NASH from NAFLD." (PMID 36831184, 2023). "Steatosis is also associated with alterations of the GH/IGF-1 axis." (PMID 30200408, 2018). "Histopathological changes (lymphocytic infiltration, fibrosis, oxidative damage, steatosis, and serious cellular changes) were associated with a significant increase in hepatic lipid peroxidation levels, which were restored to normal values following IGF-1 therapy." (PMID 28472963, 2017). "Hepatic IGF-1 mRNA was notably lower in individuals with higher steatosis and NAS, inversely correlating with glucose parameters." (PMID 40520449, 2025). "Multivariate logistic regression analysis found IGF-1 < 130 ng/mL as an independent predictor of the degree of steatosis (OR = 0.015, p ≤ 0.01) and IGF-1 < 110 ng/mL as an independent predictor of NASH (OR = 0.096, p ≤ 0.02)." (PMID 36831184, 2023). "The GH/IGF-1 ratio assessment revealed a significant reduction in patients with steatosis grade 2–3 compared with those with steatosis grade 1 (p < 0.001)." (PMID 36831184, 2023). "For steatosis, it was seen that for IGF-1 < 130 ng/mL, the area below the ROC curve was found to be 0.75, while sensitivity and specificity were 0.68 and 0.79, respectively." (PMID 36831184, 2023). "Like serum levels, hepatic IGF-1 mRNA levels also decline with increasing degrees of steatosis, steatohepatitis, and fibrosis in adults, whereas IGF-1R and GHR expression does not appear to change with increasing severity of NAFLD." (PMID 37520312, 2023). "At the same time, IGF-1 mRNA was significantly reduced in patients with NASH compared to those in patients with simple steatosis (approximative reduction of 66%, p < 0.05)." (PMID 36831184, 2023). "In different experimental and human studies, decreased levels of GH and IGF-1 were associated with increased severity of NAFLD and steatosis." (PMID 36831184, 2023). "Physiologic actions of IGF-1 include suppression of inflammatory and fibrogenic pathways important in the evolution from steatosis to steatohepatitis and fibrosis." (PMID 37520312, 2023). "Rodent models of impaired hepatic GH signaling show the development of steatosis, sometimes accompanied by inflammation, hepatocellular damage, and fibrosis, and these changes are ameliorated by treatment with GH and/or IGF-1." (PMID 37520312, 2023). "IGF1/IGFBP3 ratio revealed a tendency to decrease in patients with steatosis, confirmed by ultrasound and increased aminotransferases, as well as the ones with NAFLD and portal fibrosis." (PMID 29702590, 2018). "Recently, the same group of researchers investigated the effect of IGF1 on NASH and cirrhotic mice models and demonstrated that IGF1 ameliorated steatosis, inflammation, and fibrosis." (PMID 29702590, 2018). "IGF1 levels were lower in steatosis with normal (SNLFT) and disturbed liver function tests (SDLFT) in humans with NAFLD." (PMID 29702590, 2018). "In humans, GHR and IGF-1 levels were determined in liver samples of 29 obese patients with non-alcoholic steatohepatitis (NASH) or simple steatosis." (PMID 30206761, 2018).
steatosis (continued). "Up to now it is not completely clear, what distinguishes the effects of IGF2 from the ones of IGF1 in steatosis." (PMID 27199763, 2016). "Reduced GH signaling in liver caused reduced Igf-1 expression and impaired growth, as well as increased levels of CD36 and Vldlr, which is consistent with the reported steatosis and altered lipid profile in the liver of Nestin-Cre mice." (PMID 26275221, 2015). "Overall, these prior studies suggest that maintaining optimal IGF-1 levels through GH replacement therapy may be an effective treatment option for GHD patients with liver impairment and associated steatosis and fibrosis." (PMID 38370349, 2024). "The liver is known to be protected from steatosis under the influence of high GH/IGF-1." (PMID 38709454, 2024). "Evaluation of histological factors and IGF-1 levels showed that the levels of IGF-1 increased significantly with the steatosis grade (r = 0.262, p < 0.001), while decreasing significantly with increasing lobular inflammation (r = −0.134, p < 0.001) and fibrosis (r = 0.362, p < 0.001)." (PMID 36831184, 2023). "Nevertheless, in this study, patients with steatosis still presented lower IGF-1 levels." (PMID 36831184, 2023). "Thus, in simple steatosis and early NASH, many of the body composition and metabolic features predisposing to NAFLD/NASH may also contribute to reduced GH and/or IGF-1." (PMID 37520312, 2023). "Indeed, the relationship between IGF-1 and steatosis may become less evident when IGF-1 SDS is applied." (PMID 36831184, 2023). "IGF-1 SDS levels were inversely related to the grade of liver inflammation (r = −0.24, p < 0.02), steatosis (r = −0.37, p < 0.002), ballooning (r = −0.47, p < 0.001), and NAS (r = −0.49, p < 0.001)." (PMID 36831184, 2023). "On the other hand, in the presence of steatosis, the abolishment of NRG1 or PAK1 effects affected IGF1 since in steatotic livers from the BD+anti-NRG1+LT and BD+anti-PAK1+LT groups, IGF1 levels were lower than in the BD+LT group." (PMID 35625715, 2022). "Children with NASH showed significantly lower levels of IGF-1 SDS (−1.3 vs. 1.0, p < 0.05) and IGF-1/IGFBP-3 ratio (0.086 vs. 0.14, p < 0.02) and higher grades of steatosis (2.64 vs. 1.84, p < 0.001), lobular inflammation (1.64 vs. 1.14, p = 0.002), and ballooning (1.79 vs. 0.44, p < 0.001)." (PMID 36831184, 2023). "IGF-1 did not entirely reverse steatosis or some features of inflammation, however, supporting independent roles for both GH and IGF-1 in the pathogenesis of NAFLD and NASH." (PMID 37520312, 2023). "The important role of the reciprocal shift in IGF1/GH and subsequent GH-mediated WAT lipolysis to the development of steatosis in these model systems is based on studies in mice with the loss of hepatocyte GHR signaling, due to the congenital liver-specific knockout of JAK2 (JAK2L)." (PMID 34685512, 2021). "Hepatic IGF-1 expression levels reflecting GH action were significantly lower and fasting glucose concentrations higher in patients with NASH than in patients with simple steatosis." (PMID 30206761, 2018). "Body weight was correlated with glycemia, liver weight, Steatosis score, Rheb and Igf-1 expression, and gastrocnemius weight (data not shown)." (PMID 27445979, 2016). "In their model of liver-specific GHR deletion, Fan and colleagues demonstrate that rescue of GHR expression reverses the liver phenotype, whereas infusion of IGF-1, which lowers serum GH to normal but does not restore hepatic GH signaling, is not sufficient to correct hepatic steatosis." (PMID 37520312, 2023). "Moreover, the univariate binary logistic analysis revealed a negative statistically significant relationship between IGF-1 levels and the presence of severe steatosis." (PMID 36831184, 2023).
steatosis (continued). "However, in the same mice models, the steatosis grade was not reduced after 2 weeks of IGF-1 infusion." (PMID 36831184, 2023). "Next, we evaluated whether, in addition to the benefits in terms of APT, glycogen and phospholipids induced by the lipid treatment in steatotic livers, changes in growth factors (HGF, IGF1 and VEGFA) could explain the enhanced benefits conferred by the lipid treatment in the presence of steatosis." (PMID 34444713, 2021). "Whether the observed downregulation of IGF1 in steatotic patients has a functional role in steatosis development, however, has not been evaluated sufficiently in the literature." (PMID 27199763, 2016). "In the present study, we demonstrated that insulin and/or IGF1 signaling mediated through Irs1 is directly contributed to the development of HCC, independent of the development of steatosis." (PMID 28710407, 2017). "Although previous studies have shown the role of insulin/IGF1 signaling and the downstream molecules in HCC development, the possibility of the effect of steatosis and surrounding hepatocellular damage could not be excluded in these studies." (PMID 28710407, 2017). "In addition, it has been suggested that GH may play a direct role in hepatic DNL since IGF-1 administration in GHR knock-down mice showed no improvement in TG levels, DNL, or steatosis." (PMID 36831184, 2023).
autism (32 papers, 2013 to 2026). Persistent deficits in social interaction and communication and interaction as well as a markedly restricted repertoire of activity and interest as well as repetitive patterns of behavior. "On the other hand, although IGF1 is considered an autism susceptibility gene, its disease risk score in the SFARI database remains relatively low due to limited research on its role in autism pathogenesis." (PMID 39376742, 2024). "Changes in IGF-1 signaling are implicated in the pathogenesis of neurological and psychiatric disorders including autism and major depressive disorder." (PMID 35962006, 2022). "IGF1 has been associated with autism spectrum disorder symptoms, with IGF1-treatment proposed as an autism therapeutic intervention." (PMID 33834688, 2021). "An association has also been found between the decline of brain growth and poor response to ACTH, and, furthermore, an association between symptomatic infantile spasms and infantile autism (both conditions having low CSF IGF-1, see later)." (PMID 28954393, 2017). "The drug should probably be given at an early age when there is a deficiency of IGF-1 in autism and synaptic development is more active." (PMID 28954393, 2017). "This review summarizes the current evidence on some selected proteins such as tau protein, NFL, and BDNF as well as IGF-1 that appear to be the best protein candidates for better understanding the causes of autism, as well as for use as fluid biomarkers in the diagnosis and monitoring of ASD." (PMID 42280241, 2026). "According to the previous evidence, abnormal secretion of some hormones, such as adiponectin, leptin, ghrelin, insulin, and IGF-1 may cause changes in the growth process, especially in early life, and may be associated with the risk of autism." (PMID 38066466, 2023). "Regulatory inference using the Genie3 algorithm identified direct regulation of IGF1 by SIK1, MFRP, CHD7, NIPBL, EXOC5, and ARID2, with SIK1 and SPARCL1 significantly downregulated in autism brain organoids, potentially affecting IGF1 expression." (PMID 39376742, 2024). "Several laboratories reported already successful rescue—upon IGF-1 treatment—of cellular and behavioral alterations in mouse models of autism and neurons derived from induced pluripotent stem cells from people with neurodevelopmental disorders." (PMID 38427732, 2024). "Analysis of serum IGF-1 in children younger than 4–5 years old and of urine IGF-1 in older children would be of interest to clarify if reduced IGF-1 excretion is responsible for increased serum IGF-1 levels in autism." (PMID 35962006, 2022). "In CSF of children with autism younger than 5 years old, IGF-1 levels are reportedly lower than in controls." (PMID 35962006, 2022). "The significant elevation in IGF-1 in the autism group and the reduced proBDNF immunoreactivity in medicated subjects with autism compared to controls reinforces the involvement of those two growth factors in the pathophysiology and treatment of autism." (PMID 35962006, 2022). "In summary, we found a significant increase in serum IGF-1 and a significant decrease in serum proBDNF in young boys and girls with mild to moderate autism compared to controls." (PMID 35962006, 2022). "Mean IGF-1 immunoreactivity was significantly increased by 36% in the serum of subjects with autism compared to controls (2-tailed Mann–Whitney test, p = 0.037, n = 51)." (PMID 35962006, 2022). "The parallel fitting lines demonstrate also, that across the tested range of 5–15 years of age, serum IGF-1 levels of children with autism were higher than levels of controls." (PMID 35962006, 2022). "In contrast, serum and plasma levels of IGF-1 are reportedly higher in children with autism than controls." (PMID 35962006, 2022). "The current study aimed to compare BDNF, proBDNF and IGF-1 serum levels between children aged 5–15 years old with mild to moderate autism and controls." (PMID 35962006, 2022).
autism (continued). "It is suggested that IGF-1 increases (normalizes) IGF-1 levels which are reduced in autism at an early stage of the disease." (PMID 28954393, 2017). "In contrast, a larger study has demonstrated significantly higher levels of IGF-1 in children with autism." (PMID 27746717, 2016). "This decreased excretion might be due to the increased binding of IGF1 by IGFBP-3, which is elevated in the blood of autism patients, potentially influencing the serum concentration of IGF1." (PMID 40004071, 2025). "Recent studies suggest that IGF1 analogs or IGF2 could help alleviate social and behavioral deficits in autism, indicating a potential link between IGF signaling disruptions and autism." (PMID 39376742, 2024). "Additionally, transcriptomic analysis of brain organoids derived from autism patients demonstrated a significant downregulation of IGF1 on day 11 of in vitro culture." (PMID 39376742, 2024). "Furthermore, a study found that IGF-1 levels are lower in children with autism compared to healthy children in a control group." (PMID 39329976, 2024). "For example, the decreased prevalence of autism in FXS as a function of breastfeeding could be due to insulin-like growth factor-1 (IGF-1) levels in breast milk." (PMID 34073785, 2021). "Children with autism exhibit lower quantities of IGF-1 in cerebrospinal fluid and urine." (PMID 34073785, 2021). "Of the other measures, only CSF IGF-1 differed between children with autism and normal children." (PMID 28954393, 2017). "Moreover, there is now a clinical trial underway in which IGF-1 is being used for treatment of autism." (PMID 28954393, 2017). "Low CSF IGF-1 concentrations in children with autism at an early age may suggest a disruption of normal neurobiological mechanisms in this period." (PMID 28954393, 2017). "Remarkably, IGF-1 treatment restores synaptic deficits in neurons from 22q11.2 deletion syndrome patients, a syndrome characterized by an increased risk of SZ and ASD, as well as in a SHANK3-deficient mouse model of autism." (PMID 25061506, 2014). "Indeed, IGF-1 levels were found significantly decreased in patients with autism compared to healthy controls and IGF-1 treatment has shown beneficial effects in animal studies and was introduced as an experimental treatment for ASD." (PMID 25610379, 2014). "Moreover, IGF-1 levels significantly and positively correlated with symptoms in one scale (CARS), but not in others (CGI, ABC, Autism Diagnostic Interview (ADI), and Autism Treatment Evaluation Checklist (ATEC))." (PMID 40141202, 2025). "In addition to that, evidence for insufficient initial IGF-1 secretion assumes that the dysconnectivity characteristic of autism appears to be the result of a diminished effect of IGF-1 on neonatal neurogenesis and myelogenesis secondary to disturbances in the PI3K/AKT pathway." (PMID 35328471, 2022). "The role of neurotrophic factors in autism should be studied further, with necessary inclusion of both sexes, larger study populations (particularly medication-naïve subjects) and, in the case of IGF-1 serum levels, inclusion of subjects younger than 4 years old." (PMID 35962006, 2022). "Thus, it has been hypothesized that an inadequate supply of IGF-1 results in abnormal myelination of brain neurons leading to the development of autism." (PMID 34073785, 2021). "Low CSF IGF-1 concentrations in children with autism may point to cerebellar abnormalities." (PMID 28954393, 2017). "Thus, relatively low activities of IGF pathway molecules such as IGF1, IRS1 and IRS2 may play a role as risk factors in the pathophysiology of autistic disorder/ASD, leading to the growth and development retardation." (PMID 27483248, 2016). "In addition, it was proposed that a reduced peripartum level of IGF1 due to genetic, epigenetic, or environmental factors may be a sentinel biomarker of increased probability of the later development of autism." (PMID 27483248, 2016).